TWIST1 (twist family bHLH transcription factor 1)
Diseases named in the same sentence as TWIST1 in open-access papers (continued):
Sharing a sentence is not in itself a finding about the gene and the disease.
tumor (continued). "TWIST1 is a basic helix-loop-helix transcription factor which plays pivotal parts in manifold stages of embryonic development and considerably results in tumor initiation, primary tumor growth, and even tumor metastasis." (PMID 35242497, 2022). "Hypomethylation of the TWIST1 promoter contributes to tumorigenesis and tumor development." (PMID 35408897, 2022). "TWIST1 contributes to age-dependent inhibition of angiogenesis and lung regeneration and is involved in cellular senescence to promote tumor cell proliferation, suggesting that endothelial TWIST1 and senescence may contribute to vascular remodeling in PH." (PMID 36203755, 2022). "Taken together, these antithetical findings suggest that the role of TWIST1 in carcinogenesis might depend upon the tumor settings as well as on oncogenic drivers." (PMID 35022561, 2022). "Thus, our observations about the role of TWIST1 in enhancing NB tumor aggressiveness remain to be verified by both overexpression and KO experiments using NB cell lines without MNA with low or high MYC level, as well as with primary NB cells." (PMID 35022561, 2022). "Hence, beyond EMT and invasion, Twist1 plays a crucial role in tumorigenesis, stemness and tumor maintenance." (PMID 35892887, 2022). "We could reveal the contribution of TWIST1 in enhancing primary and secondary tumor growth and in mediating an aggressive phenotype in in vivo NB xenografts." (PMID 35022561, 2022). "The biological impact of TWIST1 on tumor growth and metastatic formation capacity was associated with alterations in the ECM composition and with the establishment of a TME supportive of tumor growth and progression." (PMID 35022561, 2022). "Further GO functional enrichment disclosed that the genes in the TWIST1 coexpression module may be involved in biological processes related to tumor degeneration, such as epithelial-mesenchymal transition (EMT) and response to TGF-β." (PMID 35894206, 2022). "Moreover, TWIST1 promotes tumor cell survival upon exposure to anticancer drugs through downregulation of the pro-apoptotic genes Bak and Bad." (PMID 36474162, 2022). "Furthermore, an additional KPC model in which Zeb1 has been deleted developed PDAC anyway, although with better tumor differentiation and retained Twist1 expression despite a reduction of Zeb2, Slug and Snail expression." (PMID 36497278, 2022). "This TWIST1-tumor-stroma signature is composed by 77 DE genes, 33 up- and 44 downregulated." (PMID 35022561, 2022). "Additionally, during EMT and tumor progression, the TWIST1 3′UTR, containing several regulatory elements, is shortened which leads to increased TWIST1 protein production." (PMID 36114510, 2022). "Alteration in PCa cell aggressiveness was also observed in both cell lines after PPAT explant co-culture, demonstrated by a significant increase in expression levels of genes implicated in tumor cell proliferation (ESRRA) and in tumor invasive and metastatic potential (MMP-9, TWIST1)." (PMID 35978404, 2022). "Our in vivo investigations on the biological effects of TWIST1 reveal that its loss delays the primary tumor initiation and growth of NB, regardless of the number of cells and the injection site." (PMID 35022561, 2022). "In conclusion, we identified an effective combination therapy involving class I histone deacetylase and mammalian target of rapamycin complex 1/2 inhibition that effectively blocked the EMT of tumor cells by upregulating FoxO1 expression to inhibit Twist1 transcription." (PMID 33772986, 2022). "TWIST1 expression was associated with the occurrence of distant metastasis even in BM samples of patients that have received NAT, supporting the view that tumor cells undergoing EMT might have higher resistance to chemotherapy." (PMID 35158902, 2022). "In addition, a subgroup of TWIST1-target genes involved in shaping the interface between tumor cells and its stroma was described as TWIST1-tumor-stroma signature." (PMID 35022561, 2022).
tumor (continued). "The high expression levels observed in CRC support TWIST1 as a prognostic biomarker in this tumor." (PMID 34768901, 2021). "Taken together, the significantly higher number of cells in the invasive front of the tumor with TWIST-1 nuclear immunolabelling might confirm the EMT process in EcPV-2-associated epSCC." (PMID 34638929, 2021). "One clinical study reported that Twist1 was indicative of tumor cell EMT and endothelium-dependent angiogenesis in HCC, suggesting that the activation of the twist1a gene could be mediated via regulation of the EMT pathway." (PMID 34577566, 2021). "In addition, the basic helix loop helix factor Twist1 seem to be activated by hypoxia, by this effect it can induce differentiation of tumor cells into endothelial cells and promote tumor-derived vascular formation." (PMID 33466892, 2021). "Moreover, it was found that a lower T/N ratio of Twist and a lower Slug level in the tumor were both associated with a better EMFS (p = 0.006 and 0.016, respectively), albeit cccDNA levels were only associated with Twist1." (PMID 33572617, 2021). "Further, expression analysis of ZNF471 along with one epithelial and 9 mesenchymal markers in the GSE9750 dataset identified the downregulation of ZNF471 and CDH1 with concomitant up-regulation of ZEB1 and TWIST1 in tumor tissues when compared with normal samples (P<0.05)." (PMID 33566221, 2021). "Equally important, TWIST1 down-regulation inhibited tumor growth when AT84 cells were implanted either orthotopically into the tongues of mice and no clinical lesion could be observed (compared with AT84 control)." (PMID 33466385, 2021). "After literature research, the PI3K/Akt signaling pathway attracted our attention, which could significantly activate tumor metastasis and directly regulate the expression of TWIST1, one of the key markers in EMT." (PMID 35222014, 2021). "Indeed, a hypoxic environment causes that tumor cells and those from the microenvironment increase their production of factors involved in VM, such as VE-Cadherin, VEGF, MMPs, TWIST1, and HIF1A." (PMID 34359928, 2021). "However, protein and gene expression of both (TWIST1 and CSF1) are present after TWIST1 is reconstituted in the TWIST1 knockout tumor cells." (PMID 33466385, 2021). "Previous reports have shown that miR-326 might serve as a tumor suppressor via KRAS or TWIST1 suppression in solid cancers." (PMID 33741523, 2021). "Besides, the expression of lysyl oxidase and Jun N-terminal kinase also increased in these tumor cells, both of which can cooperate with TWIST1 to drive MDA-MB-231 BCCs into dormancy." (PMID 34712663, 2021). "Furthermore, FBXO45 modulated the process of EMT via mediating the ubiquitination and degradation of substantial EMT-related transcription factors, such as Twist1, Snai1/2, and Zeb1/2, in tumor cells." (PMID 35046938, 2021). "The results of this meta-analysis of the expression of SNAIL and TWIST1 transcription factors in different tumors confirmed that their increased expression affects tumor development and suggests an unfavorable treatment outcome, with TWIST1 being a better prognostic marker than SNAIL." (PMID 33915799, 2021). "Co-amplification and co-overexpression of TWIST1, a transcriptional activator of epithelial-mesenchymal-transition (EMT), and colony-stimulating factor-1 (CSF1), a major chemotactic agent for tumor-associated macrophages (TAMs), were observed in metastatic OSCC cases." (PMID 33466385, 2021). "On the other hand, some tumor microenvironment-derived factors associated with EMT promotion are known to induce VM as well, like the cytokine transforming growth factor beta (TGFB) and the transcription factor TWIST1." (PMID 34359928, 2021).
tumor (continued). "TWIST has been long considered as a transcription repressor of the EMT, and increasing the expression of TWIST1 is directly associated with tumor invasion and metastasis and mediates the loss of E-cadherin, a key epithelial marker, by binding to the promoter and blocking its transcription." (PMID 34943943, 2021). "We further investigated the mechanistic implication of TWIST1-CSF1 signaling to macrophage chemotaxis and polarization by showing a role of TWIST1 in the remodeling of OSCC tumor microenvironment via CSF1 regulation; this enhanced OSCC progression and metastasis competence in vitro and in vivo." (PMID 33466385, 2021). "Despite the evidence of miR-381-3p targeting Sox4 and Twist1, we cannot exclude other key genes that may contribute to the tumor-suppressive role of miR-381-3p." (PMID 34362391, 2021). "We considered that Twist1 could be influencing MYC expression levels, but MYC levels were similar between the two tumor models, while Twist1 was only overexpressed in the MYC/Twist1-HCC." (PMID 31933479, 2020). "In addition, Twist1 positive cells formed large dynamic rounded membrane protrusions, promoting the ability for tumor cells to traverse capillary vessels." (PMID 32391382, 2020). "MYC and Twist1 cooperate to remodel the tumor immune microenvironment." (PMID 31933479, 2020). "Recently, Twist1 and Snail1 were proved to take part in the Hh signaling in tumor-initiating cells." (PMID 31931858, 2020). "Therefore, understanding the function of transcriptional factors such as Snail1, Twist1, and Zeb1 is necessary to achieve a more comprehensive understanding of tumor EMT." (PMID 32028978, 2020). "In contrast, MKN28 cells showed a significant reduction in colony formation upon incubation with conditioned medium from SCAF#36-WT treated with 1 μM DHR, suggesting that the DHR suppression of tumor-promoting capacity was neutralized by Twist1 overexpression in CAFs." (PMID 32341496, 2020). "TWIST1 was reported to be involved in tumor cells migration." (PMID 32595631, 2020). "Our data indicate that favorable prognoses in PCa patients correlate with high CPEB1/miR-145p and low TWIST1 expression levels in their corresponding PCa-derived cell lines compared to cell lines established from tumor samples collected from patients with relapse." (PMID 33227047, 2020). "Collectively, these data suggested that Twist1 acted as a tumor promoter in HCC." (PMID 33381597, 2020). "However, antago-miR-24-3p-EVs, like anti-IL-3R-EVs, were able to significantly reduce TWIST1 expression, tumor cell number, and migration, and increase the apoptotic rate in vitro." (PMID 33040091, 2020). "As Twist1 drives tumor progression, its contribution to EMT is extensively studied across cancers." (PMID 32337580, 2020). "Overexpression of TWIST1 is reported to override Myc-induced apoptosis in tumor cells and along with the other changes, could be a compensatory response by the Pa16C KRAS-mutant pancreatic cells to survive KRAS suppression." (PMID 32576853, 2020). "In addition, ATF3 upregulates the expression of some genes involved in tumor metastasis, including FN-1, Twist-related protein 1 (TWIST1), plasminogen activator inhibitor-1, urokinase-type plasminogen activator, caveolin-1, and Slug, in MCF10CA1a cells." (PMID 32922364, 2020). "Moreover, JPX overexpression induced an increase in Twist1 expression in tumor tissues at the RNA and protein levels." (PMID 31941509, 2020). "Interestingly, in a subset of the tumor cells, Twist1 was required for the expression of other EMT-inducing TFs (Snail, Slug, Zeb2), which collaborated with Twist1 to induce pEMT, basal-like tumor progression, and metastasis." (PMID 33297508, 2020). "PCR array demonstrated that inhibiting RCC2 expression significantly decreased the expression of IGF1 and TWIST1, two well-known tumor-enhancing genes, in MCF-7 cells; conversely, overexpressing RCC2 increased the expression levels of these two genes in the transfected cells." (PMID 32565805, 2020).
tumor (continued). "Additionally, the detection of hypermethylated PIK3R5, TBX2 and TWIST1 in all four tumor tissues suggests the specificity of these biomarkers for the four TCGA cancers screened in this manuscript, and their potential as therapeutic targets." (PMID 33143142, 2020). "On the other hand, H19 is also a precursor of miR-675, and recent studies show that miR-675 promotes tumor progression by repressing twist basic helix-loop-helix transcription factor 1 (Twist1), implying that the proposed oncogenic role of H19 is mediated by the biological function of miR-675." (PMID 32872482, 2020). "A major function of Twist1 is to regulate tumor metastasis by modulating EMT." (PMID 33381597, 2020). "Additionally, studies have shown that Twist1 affects the cancerous behavior of tumor cells via the Wnt/β-catenin pathway." (PMID 31941509, 2020). "However, others experimentally demonstrated that Twist1 is sufficient to induce EMT and promote dissemination of cancer cells from primary tumor mass to secondary organs, but then Twist1 has to be switched off to allow metastatic outgrowth." (PMID 31963820, 2020). "In addition, the widespread expression of Twist1 in tumor stroma indirectly suggests its role in activated CAFs10–13." (PMID 32341496, 2020). "Moreover, SPZ1 was shown to mediate EMT signaling and regulate tumor metastasis by transactivation of TWIST1 expression." (PMID 30154425, 2019). "Additionally, the IHC staining assays and Western blot assay further confirmed the Twist1 proteins were decreased in the tumor xenografts of the salinomycin-treated mice." (PMID 31718679, 2019). "Additionally, IHC staining of Src-1 or Twist1 in tumor tissues demonstrated that Src-1 and Twist1 was highly expressed in NPC patients, too." (PMID 30973923, 2019). "Moreover, other studies have suggested that autophagy attenuates EMT and tumor metastasis by the degradation of Twist1 and SNAI1." (PMID 30736337, 2019). "Our RNA interaction bioinformatics prediction showed that LUADT1 could form strong base pairing with miR-15a-3p, which is a tumor-suppressive miRNA that can target Twist1." (PMID 31842825, 2019). "In this study, we have also demonstrated that immunostaining for NAT1 and TWIST1 may be of help to identify the tumor cells with EMT phenotype." (PMID 30610490, 2019). "Furthermore, to our knowledge, the exact mechanisms of Twist1 in modulating tumor metabolism remain elusive." (PMID 31383001, 2019). "P62 can promote tumor cell growth and metastasis in a Twist1-dependent manner." (PMID 31024564, 2019). "It has been suggested that the TWIST1 enhances metastatic ability of tumor cells in ESCC." (PMID 31470870, 2019). "TWIST1, a helix-loop-helix domain containing transcription factor, carries a key regulator role in organogenesis and its hypermethylation and overexpression have been identified in several tumor types." (PMID 30610490, 2019). "In addition, previous study has shown that Twist1 expression is directly associated with LMP1 expression and tumor metastasis clinically in NPC patients." (PMID 30973923, 2019). "SPZ1 expression alone was shown to activate TWIST1 expression and initiate EMT, implying that SPZ1 may, to some extent, exert a regulatory effect on tumor progression induced by TWIST1 expression." (PMID 30154425, 2019). "During the TWIST1-promoted ovarian cancer metastasis, discoindin domain receptor 2 was upregulated to increase activity of matrix modeling enzymes and the cleavage of FN, leading to elevated migratory and invasive activities of tumor cells." (PMID 31861892, 2019). "Its relationship with Twist1 is important in cancer high stage and the size of tumor." (PMID 32099601, 2019). "Confocal fluorescence imaging was used to examine the interaction between SPZ1 and TWIST1 in immunostained samples of tumor masses and adjacent healthy liver tissues from patients with HCC, showing TWIST1 protein expression (red) and SPZ1 expression (green) in HCC cells." (PMID 30154425, 2019).
tumor (continued). "Xenograft tumor models were used to assess the oncogenic role of TWIST1-ceRNET in vivo." (PMID 31645542, 2019). "Indeed, a direct consequence of chronic deficient autophagic flux in our experimental cells is the accumulation of the autophagy substrate p62 shown to interact with TWIST1 protein to promote its stabilization and tumor cell proliferation." (PMID 31101737, 2019). "Consistent with the CSC hypothesis, TWIST1 promotes tumor sphere formation, a functional indication of the self-renewal ability and CSC population." (PMID 29455655, 2018). "Twist1 expression is transcriptionally regulated by the Nk2 homeobox 2.8 (Nkx2.8) transcription factor, which is a tumor suppressor; Nkx2.8 directly binds to the Twist1 promoter region and transcriptionally represses its expression, subsequently inhibiting the EMT." (PMID 30463358, 2018). "Interestingly, C3 expression in tumor cells is transcriptionally regulated by twist basic helix–loop–helix transcription factor 1 (TWIST1), which binds to the C3 promoter and enhances its expression." (PMID 30061895, 2018). "To test whether the tumor-promoting effects of MMSET are mediated by Twist1 in EC, we examined the protein expression of Twist1 and its downstream effectors Vimentin and E-cadherin in EC cells following either MMSET overexpression or knockdown." (PMID 29796186, 2018). "The influence of the methylation of EMT-associated genes (TWIST1, SNAI1 and SNAI2) and the clinico-histopathological features of invasive BC, namely, age, HR and HER2 status, tumour histology and Ki-67 proliferative index on tumour grade were assessed in a multivariate model." (PMID 30189837, 2018). "Moreover, the median survival time of HCT-8/V tumor-bearing mice was increased by 56% after the Twist1 siRNA treatment." (PMID 28881781, 2017). "In addition to these cardinal EMT pathways, Twist1 also regulates other aspects of the tumor metastasis process via different signaling pathways." (PMID 28099910, 2017). "Besides, we demonstrated that up-regulation of Twist1 in esophageal fibroblasts significant increased the ability of fibroblasts to promote tumor progression, whereas down-regulation of Twist1 in esophageal CAFs impaired their tumor-promoting ability." (PMID 29029429, 2017). "Furthermore, with analysis by a real-time qPCR, key transcriptional factors of the EMT such as Snail1, Snail2, Twist1, Twist2, Zeb1, and Zeb2, were found to be markedly expressed in Tg-6m tumor cells when normalized to Tg-3m tumor cells." (PMID 28419107, 2017). "Twist1 silencing increased the Rh123 accumulation in the tumor cells." (PMID 28881781, 2017). "Hypermethylation of TWIST1 and TWIST2 promoters in the tumor stroma may represent an alternative mechanism for regulation of TWIST1." (PMID 29258163, 2017). "Interestingly, ECM stiffness, a mechanosensory signal, was shown to activate EMT via TWIST1 and lead to increased tumor invasion and metastasis." (PMID 28085222, 2017). "Similarly, in colorectal cancers, Twist1 expression was found to be mainly restricted to tumour–stroma." (PMID 28544627, 2017). "HCT-8/V tumor-bearing mice were used to verify the drug reversal effects of Twist1 silencing." (PMID 28881781, 2017). "Next, we detected the expression of VE-cadherin to analyse the correlation between HMGA2 and VE-cadherin not only because Twist1 promotes VM formation by targeting its promoter but also due to its frequent overexpression in tumour tissues and its importance in both tumour invasion and VM formation." (PMID 28533522, 2017). "This phenotypic switch including loss of cell contact, upregulation of N-cadherin, Vimentin, Snail, Slug, Twist1 and decreased expression of E-cadherin inversely is important for cell for cancer cells to migrate, invade and induce tumor dissemination from primary site to a secondary organ." (PMID 28032603, 2017).